INS (insulin)
Diseases named in the same sentence as INS in open-access papers (continued):
Sharing a sentence is not in itself a finding about the gene and the disease.
prostate carcinoma (232 papers, 2002 to 2026). A carcinoma that arises from epithelial cells of the prostate gland. "Physical activity is associated with reduced risk of prostate cancer (PCa) progression and death; changes in insulin sensitivity and inflammation are potential mediating mechanisms." (PMID 41546786, 2026). "The association of prostate cancer with deranged lipid profile and insulin levels is inconsistent and not well understood." (PMID 39781138, 2024). "In conclusion, the result of this study has shown a significant positive association of serum insulin and insulin-like growth factor-1 levels with prostate cancer Gleason score and grade." (PMID 39781138, 2024). "Other GWAS traits associated at this locus comprise sex hormone-binding globulin levels, male-pattern baldness, fasting insulin, estradiol levels with the same effect direction and prostate cancer risk." (PMID 38233393, 2024). "Our research also observed positive association of insulin and insulin-like growth factor-1 levels with Gleason score and grade of prostate cancer." (PMID 39781138, 2024). "Within the burgeoning field of prostate cancer research, various intricate mechanisms have been proffered to explicate the plausible causal link between insulin and this malignancy." (PMID 38054148, 2023). "Insulin users (including all types of insulin) versus non-insulin users had increased risk for pancreas, liver, kidney, stomach, and respiratory cancer, but decreased risk for prostate cancer." (PMID 35158824, 2022). "We downgraded the evidence on insulin signalling and prostate cancer to very low certainty due to: risk of bias, which was at least moderate for all studies; heterogeneity between the studies; and imprecision (1 level for each)." (PMID 34822385, 2021). "All studies investigated the association of insulin biomarkers on total prostate cancer risk and advanced PCa, and all but one study investigated localised prostate cancer." (PMID 34822385, 2021). "Higher c-peptide levels (surrogate marker for endogenous insulin production) are associated with increased risk of PCSM as well as high-risk prostate cancer (Gleason ≥ 7)." (PMID 32056047, 2020). "A large prospective survival analysis reported that higher serum C-peptide concentrations, a surrogate of insulin levels, were associated with increased prostate cancer-specific mortality." (PMID 31052319, 2019). "We also identified and replicated multiple prostate cancer risk-associated interactions that involved DNA repair, PD-1 (programmed cell death protein 1) signaling, and insulin regulation pathways." (PMID 31537791, 2019). "High serum insulin levels have been reported to be associated with an increased risk of prostate cancer." (PMID 31562809, 2019). "We anticipated detection of an interaction between c-peptide, a biomarker for insulin, and 25(OH)D with prostate cancer, as we have found high levels of c-peptide to be associated with a near two-fold increased risk for high-grade prostate cancer." (PMID 28417914, 2017). "Another recent study associate C-peptide plasmatic levels (as indirect marker of insulin) with higher risk of death in prostate cancer patients." (PMID 28389628, 2017). "Components of MetS are linked to an increased risk of prostate cancer and MetS-related biomarkers such as insulin, insulin-like growth factor-1 (IGF-1), leptin and adiponectin are implicated in the involvement of tumorigenesis." (PMID 27349496, 2016). "In a study of prostate cancer xenografts, the ketogenic diet was shown to cause lowered insulin and IGF, decreased phosphorylation of AKT, and slowed tumor growth." (PMID 26192445, 2015). "Breast and prostate tumour cells are responsive to insulin, and elevated insulin (hyperinsulinaemia) is associated with breast and prostate cancer risk." (PMID 25376984, 2014). "A gene-dosage effect is present as this CNV is associated with urine testosterone level, male insulin sensitivity, fat mass, and prostate-cancer risk (as summarized by Xue)." (PMID 23927372, 2013).
prostate carcinoma (continued). "More recently, the insulin-sensitising class of drugs, thiazolidinediones, has also been associated with improved survival of diabetic prostate cancer patients revealing several potential nodes of therapeutic intervention which warrant further research." (PMID 22548055, 2012). "Our findings suggest a role of the insulin signaling pathway in prostate cancer and can hence be relevant for both novel diagnostic as well as therapeutic approaches in this malignancy." (PMID 23251408, 2012). "FOXO1 only appears in the pathways of Module 4, it is associated with prostate cancer and insulin signaling pathway." (PMID 20419126, 2010). "We examined the relation between risk of prostate cancer and a single nucleotide polymorphism (SNP) marker in INS in a case–control study." (PMID 12610512, 2003). "In this case–control study conducted in China, men with insulin levels in the highest tertile had a 2.5-fold increased risk of prostate cancer compared to men in the lowest tertile after adjusting for IGF-I and anthropometric factors." (PMID 12610512, 2003). "We examined the associations between prostate cancer with polymorphisms of the insulin gene (INS) and its neighbouring genes, tyrosine-hydroxylase and IGF-II (TH and IGF2)." (PMID 12610512, 2003). "Markers in the neighbouring genes of INS showed only null to modest associations with prostate cancer." (PMID 12610512, 2003). "It is unlikely, since INS showed the strongest association with risk of prostate cancer, as the strength of association dropped off with the two neighbouring genes." (PMID 12610512, 2003). "Elevated insulin levels are associated with increased risk of prostate cancer and increased risk of metastatic disease in women with breast cancer." (PMID 12232754, 2002). "Physical activity improves insulin sensitivity and might reduce the risk of aggressive prostate cancer progression." (PMID 39781138, 2024). "In contrast, higher insulin levels have been associated with a higher rate of prostate cancer." (PMID 38774165, 2024). "It is also worth noting that in vitro studies have demonstrated that insulin acts as a growth-stimulating factor for prostate epithelial cells, and its elevated levels are associated with a higher risk of both the development and recurrence of prostate cancer." (PMID 39682196, 2024). "There were six prospective observational studies which investigated whether biomarkers of circulating insulin were associated with prostate cancer risk at follow-up." (PMID 34822385, 2021). "Although the underlying mechanisms remain unclear, skeletal muscle mass may be associated with insulin growth factor signaling, host immunity, systemic inflammation, and hormonal activity, which are related to the aggressiveness of prostate cancer." (PMID 32363164, 2020). "In addition, polymorphisms in the INS have been reported to be associated with increased prostate cancer risk." (PMID 32850701, 2020). "Higher insulin and glucose levels are associated with a worse prostate cancer prognosis." (PMID 32056047, 2020). "Conversely, a high-calorie diet (45 kcal% fat) promoted prostate cancer progression in genetically susceptible Pten haploinsufficient mice with increasing inflammatory response in the presence of enhanced insulin response to chronically elevated insulin levels." (PMID 31052319, 2019). "In contrast, we found a decreased risk of prostate cancer for men on insulin or sulfonylurea." (PMID 27770555, 2017). "Minimizing excess adipose tissue and the reduction of blood glucose and insulin levels may be a potent method of reducing prostate cancer risk and improving outcomes." (PMID 26977321, 2016). "The effect of rye whole grain may be related to the inhibition of prostate cancer progression caused by decreased exposure to insulin, as indicated by plasma insulin and urinary C-peptide excretion." (PMID 26075268, 2015).
prostate carcinoma (continued). "Potential biological mechanisms underlying the association between BMI and prostate cancer could act through insulin, IGF-I, and testosterone." (PMID 25881129, 2015). "It has been suggested that dietary fiber may reduce prostate cancer risk possibly by increasing circulating levels of sex hormone-binding globulin and improving insulin sensitivity." (PMID 26315558, 2015). "Salicylates are able to improve insulin sensitivity in obese mice and in humans affected by type 2 diabetes and they have also been shown to reduce the risk of several cancers including colon, breast, and prostate cancers." (PMID 27478687, 2014). "Insulin vs. other glucose-lowering agents and risk of prostate cancer." (PMID 24282613, 2013). "Previous observational studies have shown that insulin therapy may modify the risk of prostate cancer (PCa)." (PMID 24282613, 2013). "Fiber has been implicated in prostate cancer etiology; fiber increases sex hormone-binding globulin and improves insulin sensitivity, both of which may decrease risk of aggressive prostate cancer." (PMID 23213538, 2012). "Another interest is whether a higher insulin level is associated with a higher incidence of prostate cancer." (PMID 22792092, 2012). "Similarly, the increase in incident prostate cancer observed in a Swedish cohort of MetS males was associated with high SUA and insulin levels, and both SUA and insulin were significant parallel prospective markers of risk for prostate cancer." (PMID 23369448, 2012). "Therefore, the simultaneous presence of high insulin and leptin levels and low testosterone levels explains the reduced risk of incident tumours, but the increased risk of progression in existing prostate cancer tumours." (PMID 21266978, 2011). "Insulin is hypothesised as a risk factor of prostate cancer because of its structural and regulatory relations with the IGF system." (PMID 12610512, 2003). "High insulin levels are linked with increased cancer risk, including prostate cancer." (PMID 12610512, 2003). "If the polymorphism at +1127 INS-PstI increases prostate cancer risk via altered insulin levels, this may explain its lack of association with prostate cancer among the diabetics." (PMID 12610512, 2003). "Given our underlying hypothesis that insulin drives BPH pathophysiology, we completed a post hoc analysis of the Reduction by Dutasteride of Prostate Cancer Events (REDUCE) Trial to assess the association between insulin resistance and both prostate size at baseline and PV growth over time." (PMID 40955380, 2025). "Our study had small sample size, thus may not be generalized to other ethnicities; hence, multicenter studies examining the association of lipid profile and serum insulin, insulin-like growth factor-1 levels with benign prostatic hyperplasia or prostate cancer are warranted." (PMID 39781138, 2024). "Chronically elevated insulin levels could facilitate tumor progression and development of comorbidities, including cardiovascular disease, a major cause of death in patients with prostate cancer." (PMID 39180334, 2024). "Besides, high intake of dietary fiber in healthy plant-based diets could reduce the risk of prostate cancer by improving insulin sensitivity and reducing the bioavailability of insulin-like growth factor-1 (IGF-1)." (PMID 38902815, 2024). "Therefore, it is plausible that metformin may act via insulin-independent pathways to reduce the risk of advanced prostate cancer." (PMID 27547763, 2016). "The polymorphism of INS may play a role in the aetiology of prostate cancer." (PMID 12610512, 2003). "Preclinical studies consistently demonstrate that carbohydrate restriction and KD can slow tumor growth, modulate key oncogenic pathways such as PI3K/AKT/mTOR, reduce systemic insulin signaling, and enhance survival in prostate cancer models." (PMID 42194907, 2026). "Häggström and associates, in 2016, evaluated metformin users, sulfonylurea users, and insulin users in prostate cancer prevention." (PMID 40572709, 2025).
prostate carcinoma (continued). "The relationship between insulin use and prostate cancer outcomes is less clear and requires further study." (PMID 40693585, 2025). "There is clear precedent for dogs playing a translational role in endocrine research relevant to human health, including the discoveries of insulin and androgen ablation for regression of prostate cancer." (PMID 40671157, 2025). "The nutrient-sensitive kinase mTORC1 is upregulated in nearly 100% of advanced human prostate cancers, and this kinase is activated by leucine, insulin, IGF-1, and glucose." (PMID 39941741, 2025). "Metformin has been related to decreasing prostate cancer, while Insulin is found to increase prostate cancer." (PMID 38774165, 2024). "In this study, we observed significantly elevated insulin and insulin-like growth factor-1 levels in both benign prostatic hyperplasia and prostate cancer groups." (PMID 39781138, 2024). "Previously, we found low-carbohydrate diets slowed prostate cancer (PC) growth and increased survival vs. a Western diet in mice, by inhibiting the insulin/IGF-1 axis." (PMID 38082056, 2024). "The KEGG pathway analysis exposed several critical pathways, including those related to prostate cancer, endocrine resistance, and insulin signaling pathways, further elucidating the molecular interplay between Baikal skullcap constituents and T2DM." (PMID 38612466, 2024). "This study aimed to analyze the serum levels of lipids, insulin, insulin-like growth factor-1 (IGF-1) and testosterone and to identify their association with the risk of benign prostatic hyperplasia, prostate cancer and its grading." (PMID 39781138, 2024). "For the GDS2547 dataset, a study concerning prostate cancer, PriPath’s top predictions are insulin signaling pathway (hsa04910), Ribosome (hsa03010), and Coronavirus disease (hsa05171)." (PMID 36823571, 2023). "These flavonoids have been shown to limit the growth of prostate cancer cells and reduce insulin-dependent and insulin-independent glucose uptake." (PMID 37835351, 2023). "These facets collectively paint a rich and complex tapestry of interactions, offering a deeper understanding of the intricate relationships between insulin and the pathogenesis of prostate cancer." (PMID 38054148, 2023). "The hormone ghrelin, whose expression is regulated by insulin in cancer cells, stimulates cell proliferation in prostate cancer cell lines." (PMID 37329212, 2023). "This growing body of knowledge robustly affirms the pivotal role of insulin in the initiation and subsequent neoplastic progression of prostate cancer." (PMID 38054148, 2023). "We identified 3152 potentially eligible studies on insulin sensitivity and prostate cancer but only six of these studies met our inclusion criteria." (PMID 34822385, 2021). "Meta-analysis performed on a total of 1143 men in the prostate cancer group and 1692 men in the control group has shown that patients with prostate cancer had insulin level significantly higher in comparison with the control group." (PMID 33921222, 2021). "And for KEGG analysis, the top five descriptions were prostate cancer (hsa05215), the insulin signaling pathway (hsa04910), small-cell lung cancer (hsa05222), the adipocytokine signaling pathway (hsa04920), and the glucagon signaling pathway (hsa04922)." (PMID 34540994, 2021). "Previously published work has used EVs to assess changes in biomarkers of brain insulin signaling in clinical trials of a protein restriction diet for prostate cancer, exenatide for PD, and intranasal insulin for AD." (PMID 32268604, 2020). "Another potential mechanism, which has been supported by recent research, is that dietary protein decreases insulin sensitivity and promote prostate cancer cell tumor growth in animal models, which in turn affect the PSA levels." (PMID 32359345, 2020). "According to this new analytical procedure, four signaling pathways for olfactory transduction, prostate cancer, insulin secretion, and amphetamine addiction were found out." (PMID 31485258, 2019).
prostate carcinoma (continued). "The relationship between ARHGEF11-activated Rho with leukemia, prostate cancer, and embryonic development and modulating insulin signaling was sequentially reported." (PMID 31612150, 2019). "As such, future studies need to elucidate the relationship between insulin levels and diet-induced prostate cancer carcinogenesis." (PMID 31052319, 2019). "Insulin has been shown to promote local androgen synthesis by prostate cancer cells, which is thought to represent a resistance mechanism to castration." (PMID 28444639, 2017). "Prostate-specific antigen concentration, waist circumference, body mass index (BMI), lipid profile, glucose level, and insulin level were determined in 153 patients with prostate cancer and 80 controls." (PMID 28717736, 2017). "Dietary protein restriction (PR) increases insulin sensitivity and suppresses prostate cancer cell tumor growth in animal models, providing a rationale for clinical trials." (PMID 28921841, 2017). "High insulin levels are known to be an adverse prognostic factor for a number of cancers, including breast, colon, and prostate cancer, and metformin has been shown to be able to lower systemic insulin levels, even in non-diabetic patients." (PMID 28444639, 2017). "Studies have shown that even short-term use of ADT significantly increases fat mass and decreases insulin sensitivity in men with prostate cancer." (PMID 28444639, 2017). "Our study demonstrates that a Western 23% HFD increases fat mass, reduces insulin tolerance, increases LNCaP human prostate cancer xenograft growth, and decreases survival to ethical endpoints in male Rag1−/− mice." (PMID 28352127, 2017). "Intervention of IGF1/insulin-phosphatidylinositol 3-kinase-Akt signaling was reported to be of clinical value for prostate cancer." (PMID 27475327, 2016). "Prostate cancer cell lines cultured in the presence of insulin induce steroidogenesis and increase their expression of PSA." (PMID 27599544, 2016). "Elevated insulin also correlates with increased risks of prostate cancer diagnosis and recurrence after treatment." (PMID 26977321, 2016). "IGF-I upregulates the insulin pathway, stimulating the growth and progression of prostate cancer cells." (PMID 26977321, 2016). "Much support exists for exercise interventions in improving MetS variables in insulin-resistant adults, but less evidence is available in men with prostate cancer." (PMID 27349496, 2016). "This corresponds to observations in a prostate cancer LNCaP cell line or insulin secreting INS-1E cell line." (PMID 27450545, 2016). "Long-acting insulin therapy not only decreased the development of lung and prostate cancer but also reduced oncogenesis in GI malignancies like liver and colorectal cancer." (PMID 25978841, 2015). "Combination insulin decreased the risk of colorectal (AHR = 0.47 (0.25–0.88)) and prostate cancer (AHR = 0.19 (0.05–0.77) (all p<0.05)." (PMID 25978841, 2015). "In this study, we tried to determine the association of the GNMT polymorphisms STRP1, INS/DEL and rs10948059 and prostate cancer risk in Americans of European ancestry." (PMID 24800880, 2014). "Fasting plasma insulin, in particular, was linked to BPH and all subtypes of prostate cancer namely: incidental, aggressive and lethal prostate cancer (Hammarsten & Högstedt 2002)." (PMID 25674400, 2013). "Previous experimental studies have demonstrated that insulin can promote cellular growth and proliferation of prostate cancer cell and receptors for insulin are highly expressed on various types of cancer cell such as PCa." (PMID 24282613, 2013). "Recent studies have revealed the essential role of PKD3 in the progression of prostate cancer and insulin-independent basal glucose uptake in L6 skeletal muscle cells." (PMID 23561540, 2013). "We investigated the composition of molecules important for insulin signal transduction in prostate cancer in comparison to benign prostate tissue." (PMID 23251408, 2012).